MIIP (migration and invasion inhibitory protein)
Diseases named in the same sentence as MIIP in open-access papers (continued):
Sharing a sentence is not in itself a finding about the gene and the disease.
ovarian carcinoma (2 papers, 2016 to 2024). A malignant neoplasm originating from the surface ovarian epithelium. "Co-cultivation of the VM strain with ovarian cancer cells has revealed the bacterium’s ability to invade cancer cells and stably express the MIIP protein, concomitant with inhibiting ovarian cancer cell proliferation and migration." (PMID 38372808, 2024). "Our results revealed that the VM strain demonstrated superior growth performance, successfully invaded ID8 ovarian cancer cells, and expressed MIIP, consequently suppressing cell proliferation and migration." (PMID 38372808, 2024). "The research aims to confirm the anti-tumor effects exerted by VNP20009-AbVec-Igκ-MIIP and to explore new breakthroughs for the challenges faced by current ovarian cancer drug treatment, such as drug resistance, low specificity, and side effects." (PMID 38372808, 2024). "Moreover, VM specifically targeted tumor sites and expressed MIIP which further reduced the tumor volume of ovarian cancer mice (p < 0.01), via the downregulation of epidermal growth factor receptor (EGFR), Ras, p-MEK, and p-ERK." (PMID 38372808, 2024). "Therefore, MIIP may be a promising molecular target in ovarian cancer therapy." (PMID 38372808, 2024). "Finally, our experiments showed that MIIP could reduce MMP9, which is consistent with the recent report of Rac1/Pak1/p38/MMP axis in ovarian cancer oncogenesis." (PMID 27760566, 2016).
allergic disease (1 paper, 2022). An immune response that occurs following re-exposure to an innocuous antigen, and that requires the presence of existing antibodies against that antigen. "Our study newly identified six loci associated with allergic diseases (MIIP, CXCR4, SCML4, CYP1B1, ICOS and LINC00824) and four pleiotropic loci associated with both autoimmune and allergic diseases (PRDM2, G3BP1, HBS1L and POU2AF1)." (PMID 35753705, 2022).
Cachexia (1 paper, 2024). Severe weight loss, wasting of muscle, loss of appetite, and general debility related to a chronic disease. "Moreover, no remarkable differences in final body weight were observed between HCT116 (MIIP+/− or WT) + adipocytes and HCT116-alone (MIIP+/− or WT) groups, indicating that cachexia did not occur during the assays." (PMID 38245780, 2024).
lung adenocarcinoma (1 paper, 2016). A carcinoma that arises from the lung and is characterized by the presence of malignant glandular epithelial cells. "Furthermore, the higher MIIP protein expression predicts a better overall survival of Stage IA-IIIA lung adenocarcinoma patients who underwent radical surgery." (PMID 26824318, 2016). "The negative correlation between MIIP and EGFR protein expression was validated in lung adenocarcinoma samples." (PMID 26824318, 2016).
mucinous adenocarcinoma (1 paper, 2024). An invasive adenocarcinoma composed of malignant glandular cells which contain intracytoplasmic mucin. "Subsequently, we analyzed MIIP expression in tissue microarrays (TMAs) consisting of 172 samples from CRC patients (148 adenocarcinomas and 24 mucinous adenocarcinomas) and 47 samples from matched adjacent normal tissues using IHC staining." (PMID 38245780, 2024).
squamous cell carcinoma (1 paper, 2014). A carcinoma arising from squamous epithelial cells. "The results revealed that the MIIP mRNA expression levels in adenocarcinoma were significantly higher than those in squamous cell carcinoma (P=0.002)." (PMID 25360165, 2014).
triple-negative breast carcinoma (1 paper, 2022). An invasive breast carcinoma which is negative for expression of estrogen receptor (ER), progesterone receptor (PR), and human epidermal growth factor receptor 2 (HER2). "In the present study, we found MIIP is a favorable indicator of prognosis in triple-negative breast cancer." (PMID 36130933, 2022). "Our findings unravel a novel mechanism by which MIIP suppresses tumorigenesis in triple-negative breast cancer, and MIIP is thus a promising molecular biomarker or therapeutic target for the disease." (PMID 36130933, 2022). "MIIP could inhibit tumor angiogenesis, proliferation, and metastasis of triple-negative breast cancer cells in vivo and in vitro." (PMID 36130933, 2022).
tumor (15 papers, 2014 to 2026). "We also revealed the underlying mechanism through which MIIP exerts its tumor-suppressive role by interacting with PP1α and facilitating dephosphorylation of AKT, thereby leading to attenuation of AKT-mTOR axis." (PMID 31092266, 2019). "MIIP expression levels were significantly associated with pathology and tumor stage, with reduced MIIP mRNA expression levels detected in advanced tumor stage samples." (PMID 25360165, 2014). "Considering β-catenin could transcriptionally activated VEGFA and MMPs to regulate tumor angiogenesis and metastasis, we wondered whether β-catenin is implicated in MIIP-elicited tumor-suppressing effect in TNBC." (PMID 36130933, 2022). "MIIP downregulation stimulates tumour cells to secrete glycosylated AZGP1 protein, which acts on adipocytes to activate the intracellular cyclic adenosine monophosphate (cAMP)-PKA signalling pathway-subsequently inducing adipocyte browning and lipolysis." (PMID 41498391, 2026). "In an in vitro co-culture model, adipocytes treated with MIIP-downregulated tumor supernatant exhibited aggravated browning and lipolysis." (PMID 38245780, 2024). "As a regulator of migration and invasion, MIIP, functioning as a protein, actively engages in the remodeling of the tumor cell cytoskeleton, cellular adhesion, and modulation of signaling pathways." (PMID 38372808, 2024). "This study aims to explore the mechanism of migration and invasion inhibitory protein (MIIP) downregulation in the remodeling of tumor cell-adipocyte communication and its role in promoting CRC." (PMID 38245780, 2024). "The combined therapy demonstrated a partial inhibitory effect in tumors with normal MIIP expression, likely attributed to the tumor-suppressive functions of SR59230A and SSO." (PMID 38245780, 2024). "Migration and Invasion Inhibitory Protein (MIIP) is a newly discovered tumor-suppressive gene in recent years." (PMID 38372808, 2024). "We detected downregulation of MIIP protein levels in more than half (8/14, Samples #4, #6, #8–13) of the tumor samples compared to the corresponding normal tissues." (PMID 38245780, 2024). "Tumor tissues formed from MIIP-overexpressing MDA-MB-231 cells had decreased levels of CD34 and VEGFA, compared with that from control cells." (PMID 36130933, 2022). "More importantly, we found RGD motif is essential for the efficient tumor-suppressing capacity of MIIP." (PMID 36130933, 2022). "MIIP with deleted RGD motif diminished the ability to inhibit tumor angiogenesis, as evidenced by the results from HUVECs tube formation assay, chick embryo chorioallantoic membrane assay, and rat aortic ring assay." (PMID 36130933, 2022). "In our current study, we confirmed MIIP inhibits in vitro and in vivo growth of TNBC cells, as well as cell migration and invasion, which is consistent with the conclusions obtained from previous studies that MIIP functions as a tumor suppressor." (PMID 36130933, 2022). "Migration and invasion inhibitory protein (MIIP) has been identified as a tumor suppressor in various cancer types." (PMID 36130933, 2022). "Here, we reported for the first time that MIIP represses tumor angiogenesis by inhibiting production of VEGFA in TNBC cells." (PMID 36130933, 2022). "In the present study, we demonstrated MIIP inhibits tumorigenesis of TNBC by suppressing tumor angiogenesis, as well as cell proliferation and migration." (PMID 36130933, 2022). "Although MIIP is reported to exert tumor suppressive functions by repressing proliferation and metastasis of cancer cells, the detailed mechanism is poorly understood." (PMID 36130933, 2022). "This study not only strengthens the evidence that MIIP acts as a tumor suppressor in different types of cancer but also provides the first evidence that MIIP is a negative regulator of angiogenesis." (PMID 34931765, 2021). "Although its physiological role remains elusive, MIIP is increasingly identified as a novel tumor suppressor." (PMID 34931765, 2021).
tumor (continued). "Together, these data indicated that MIIP acts as a novel tumor suppressor that inhibits ccRCC proliferation and angiogenesis, both in vitro and in vivo." (PMID 34931765, 2021). "More recent studies identified two onco-miRNAs, 181a-5p and 181b-5p, as contributors to migration and invasion inhibitory protein (MIIP), a protein with tumor suppressor functions." (PMID 33672595, 2021). "Our combined in vitro functional and molecular studies and in vivo xenograft mouse model and clinical sample analyses provide strong evidence that MIIP is a potential tumor suppressor in ccRCC." (PMID 34931765, 2021). "Among them, cysteine-rich 61 (CYR61, also named CCN1) attracted our attention because it was located in tumor angiogenesis signaling pathway gene sets and was significantly downregulated by MIIP overexpression." (PMID 34931765, 2021). "To further confirm the roles of MIIP in ccRCC in vivo, we subcutaneously bilaterally injected OS-RC-2-MIIP, 786-O-MIIP, 786-O-shMIIP #1, and their corresponding control cells into the groin in nude mice to assess tumor development." (PMID 34931765, 2021). "In agreement with the in vitro experiments, gene set enrichment analysis (GSEA) showed that the tumor angiogenesis and hypoxia gene sets were negatively correlated with MIIP expression." (PMID 34931765, 2021). "To further confirm the tumor-suppressive function of MIIP in PCa, we examined the effects of MIIP over-expression on in vivo tumor growth in xenograft mouse model." (PMID 31092266, 2019). "Our study revealed that DIRAS3 overexpression inhibits tumor migration and invasion by up-regulating MIIP in GC cells." (PMID 30043279, 2018). "To further evaluate the positive effects of PKCε-mediated MIIP phosphorylation on tumor cell invasion, we examined MIIP-S303 phosphorylation levels in multiple colorectal cancer (CRC) cell lines with distinct invasive capability." (PMID 29038521, 2017). "Migration and invasion inhibitory protein (MIIP) gene was recently discovered candidate tumor suppress gene which located at chromosome 1p36.22." (PMID 27760566, 2016). "The median immunoreactivity score of MIIP expression in the tumor tissues was 180, and we defined a case with immunoreactivity score more than 180 as high expression, and otherwise low expression." (PMID 26824318, 2016). "A statistically significant correlation was also observed between MIIP mRNA expression and tumor stage (P=0.014), with reduced MIIP mRNA expression levels in advanced tumor stage samples, as compared with specimens from tumors at the lower stages." (PMID 25360165, 2014). "The results demonstrated that the positive percentage of MIIP protein expression was significantly reduced in advanced tumor stage samples, as compared with specimens from less advanced tumors." (PMID 25360165, 2014). "The data demonstrate that MIIP expression levels were significantly correlated with tumor staging, and reduced MIIP mRNA and protein expression levels were detected in advanced tumor stage samples." (PMID 25360165, 2014). "All these results from recent studies raise the possibility that MIIP is a putative tumor-suppressor gene, critical in cancer physiology." (PMID 25360165, 2014). "However, the combined therapy (oxaliplatin + SR59230A or SSO) significantly suppressed tumor growth in MIIP-downregulated tumors, resulting in markedly reduced average tumor size and weight compared to oxaliplatin alone treatment and scramble tumors." (PMID 38245780, 2024). "Although the tumor suppressor function of MIIP has been well studied in various types of cancer, our present study demonstrates for the first time that MIIP plays a role in regulating the secretion of lipid mobilization factors, and its aberrant expression is a key initiator of this loop." (PMID 38245780, 2024). "Furthermore, MIIP mRNA levels showed a significant reduction in most of the tumor samples compared to adjacent normal samples, indicating decreased MIIP expression in CRC tissues." (PMID 38245780, 2024).
tumor (continued). "Based on these findings, we hypothesize that VNP20009, as a targeted oncolytic bacterium, and MIIP, as an anti-cancer protein, may synergistically enhance the anti-tumor effect, potentially addressing the current shortcomings of drug therapy." (PMID 38372808, 2024). "Therefore, ITGB3/AKT/β-catenin axis is downregulated by MIIP to suppress tumor angiogenesis and EMT." (PMID 36130933, 2022). "So far, many studies reported the anti-tumor function of MIIP in different cancer types." (PMID 36130933, 2022). "More importantly, our data for the first time indicated the existence of MIIP in the CM of tumor cells, indicating MIIP could be secreted by the cells and function as a ligand of ITGB3." (PMID 36130933, 2022). "Therefore, we provide a novel understanding on the function of MIIP during tumorigenesis in the aspect of tumor angiogenesis." (PMID 36130933, 2022). "In addition, Kaplan-Meier analysis showed that higher MIIP expression in the tumor tissues from patients with ccRCC correlated with longer overall survival times (P = 0.026)." (PMID 34931765, 2021). "Moreover, Ki67 staining analysis of xenograft tumor tissues revealed significantly fewer Ki67-positive cells in the MIIP-overexpressing groups than in the control groups, whereas silencing MIIP in 786-O cells had the opposite effect." (PMID 34931765, 2021). "Consequently, the final tumor size in the MIIP-overexpression groups was significantly smaller than that in the control groups, meanwhile tumor size in the MIIP-silenced groups was larger than that in the scramble groups (P < 0.05)." (PMID 34931765, 2021). "MIIP is a novel tumor suppressor in ccRCC via negative regulation of HIF-2α-CYR61 axis." (PMID 34931765, 2021). "Taken these cytological and xenograft model studies together, MIIP plays a strong tumor-suppressive function and its downregulation may contribute to PCa progression." (PMID 31092266, 2019). "Our study further emphasized the tumor suppressive role of MIIP and illustrated a novel mechanism." (PMID 31092266, 2019). "Take together, in vivo study further emphasized the tumor suppressive role of MIIP in PCa." (PMID 31092266, 2019). "As a result, the final tumor sizes of nude mice injected with MIIP-overexpressing C4–2 and PC3 cells were much smaller than those injected with C4–2 and PC3 vector control cells (C4–2: 0.27 ± 0.09 vs 0.09 ± 0.05 g, *p<0.05; PC3: 0.63 ± 0.24 vs 0.23 ± 0.15, *p<0.05)." (PMID 31092266, 2019). "We next examined whether MIIP directly regulates tumor cell invasion and the relevant genes transcription." (PMID 29038521, 2017). "Based on the vital role of NF-κB signals and MIIP in tumor metastasis, we first examined whether MIIP is involved in the EGF-induced NF-κB activation." (PMID 29038521, 2017). "However, transwell analysis showed invasion induced by EGF was attenuated by overexpression of PP1 in HCT116 cells to a lesser extent compared with that effect from MIIP S303A, suggesting the additional function of PP1 is implicated in tumor cell invasion." (PMID 29038521, 2017). "Thus, MIIP was considered to play a major role in inhibiting epithelial tumor metastasis, which includes EC, and the inactivation of the MIIP gene in EC prompted us to further investigate its tumor suppressor functions." (PMID 27760566, 2016). "In addition, in the present study, MIIP expression levels were significantly correlated with pathology and tumor staging, suggesting a potential role for MIIP protein in the pathogenesis of NSCLC." (PMID 25360165, 2014). "Analysis of MIIP expression revealed that expression was significantly associated with pathology and tumor staging (P=0.014 and P=0.002, respectively), but not with gender, age or NSCLC differentiation status (all P>0.05), as shown in Table III." (PMID 25360165, 2014). "Therefore, we inferred that the catabolism of FFAs might be more vigorous in cells incubated with MIIP-downregulated tumor-adipocyte co-cultured supernatant." (PMID 38245780, 2024).